MASP1 (MBL associated serine protease 1)
Diseases named in the same sentence as MASP1 in open-access papers (continued):
Sharing a sentence is not in itself a finding about the gene and the disease.
glioma (3 papers, 2009 to 2021). A benign or malignant brain and spinal cord tumor that arises from glial cells (astrocytes, oligodendrocytes, ependymal cells). "Additional research is necessary to elucidate the role of MASP-1/3 in the natural history of glioma." (PMID 34671342, 2021). "Lukashova-v Zangen I el al. described that the overexpression of EPHB3 gene in ependymomas with high proliferation indices was associated with a poor outcome, and Kuraya el al. demonstrated the high expression of MASP1 gene in glioma cell line." (PMID 19607727, 2009). "Notably, MASP1 and MASP3 are highly expressed in the C6 and T98G glioma cell lines, but their expression is low in some ovarian cancer patients and the MASP1 and MASP3 expression levels are positively correlated with patient prognosis." (PMID 33869223, 2021).
glomerulonephritis (3 papers, 2018 to 2023). A renal disorder characterized by damage in the glomeruli. "In summary, our experiments revealed that MASP-1/3 is required for the development of glomerulonephritis in MRL/lpr mice." (PMID 29892304, 2018). "The absence of MASP-1/3 showed significantly reduced glomerulonephritis and albuminuria in the MRL/lpr mice of the present study; however, it did not improve their serum BUN levels or survival rate." (PMID 29892304, 2018). "Therefore, the absence of both MASP-1 and MASP-3 is protective against the development of glomerulonephritis in MRL/lpr mice." (PMID 29892304, 2018).
hepatocellular carcinoma (3 papers, 2022 to 2025). A malignant tumor that arises from hepatocytes. "Overexpression of MASP1 in hepatocellular carcinoma cell lines significantly inhibited proliferation, invasion and migration." (PMID 39910672, 2025). "Similarly, another study reported that MASP-1 was found positively correlated with a better prognosis of hepatocellular carcinoma." (PMID 35846149, 2022). "Validation of the role of MASP1 protein was also carried out in hepatocellular carcinoma (HCC) cell lines." (PMID 41439026, 2025).
IgA Nephropathy (3 papers, 2018 to 2024). "These duplexes can be tested further in various mouse models of diseases involving MASP-1 and MASP-2 such as IgA Nephropathy and experimental pneumococcal meningitis to understand the contribution of liver MASP1 and MASP2 to disease pathology in conditions where LP activations has been implicated." (PMID 32153567, 2020).
lepromatous leprosy (3 papers, 2013 to 2020). A chronic communicable infection which is a principal or polar form of leprosy. "Nevertheless, some associations were lost after multivariate logistic correction (FCN1*3C2, FCN2*AGAAGC, and FCN2*GGGCAC with lepromatous leprosy/HBV infection and MBL2*HYPA, MBL2*LYQC, FCN2*GGGCAC with non-lepromatous leprosy/HBV infection) or due to low sample size (MASP1*AC_CTG, FCN3*2B2.2A)." (PMID 33643280, 2020).
liver fibrosis (3 papers, 2018 to 2025). "Some studies in HCV infection have demonstrated a high association between MASP1 activity and severe hepatic fibrosis." (PMID 29515573, 2018). "MASP1 can be used to predict the severity of hepatitis C virus (HCV) infection and characterize the degree of liver fibrosis." (PMID 36978180, 2023).
ovarian cancer (3 papers, 2014 to 2022). A primary or metastatic malignant neoplasm involving the ovary. "Similarly, expression of the MASP1 (MASP-1, MASP-3, MAp-44, the latter lacking enzymatic activity) gene was reported to be higher in normal endometrium tissue, compared with samples from patients diagnosed with endometriosis or endometriosis-associated ovarian cancer." (PMID 35326694, 2022).
type 2 diabetes (3 papers, 2019 to 2025). "While an age- and gender-matched case-control study (n = 200) from Aarhus, Denmark, reported that increased MASP-1 was positively associated with type 2 diabetes." (PMID 37941903, 2023). "Krogh and coworkers have recently confirmed this cross-sectional association by reporting higher MASP-1 levels in persons with type 2 diabetes compared to controls." (PMID 30599058, 2019). "Similarly, children with the type 2 diabetes risk allele rs529565-C in ABO had higher MASP1 levels in our data, consistent with elevated MASP1 levels in patients with type 2 diabetes." (PMID 39972214, 2025).
angioedema (2 papers, 2013 to 2022). Swelling involving the deep dermis, subcutaneous, or submucosal tissues, representing localized edema. "These previous findings of ours harmonize with the reduced expression of PAR1 in the C1-INH-HAE patient’s laryngeal edematous tissue, which suggests an important role of MASP-1 and other plasma serine proteases in the pathogenesis of angioedema." (PMID 35787812, 2022). "Since C1INH controls several systems that influence bradykinin formation, any factor that contributes to an increase in bradykinin formation, such as activation of the contact system or MASP-1 or MASP-2, could cause an attack of angioedema." (PMID 24013493, 2013). "Important to realize for HAE-C1INH patients is that both the activity of MASP-1 and MASP-2 are controlled by C1INH and MASP-1 and MASP-2 levels are elevated during episodes of stress and infection, known initiators of angioedema episodes." (PMID 24013493, 2013).
breast carcinoma (2 papers, 2013 to 2022). "Three (LDHA, DBF4B, and MASP1) were predicted to be targeted by miRNA identified as differentially expressed in breast cancer tissues of cases compared to controls in the study of Du and collaborators or Ohzawa and collaborators." (PMID 36627894, 2022).
cystic fibrosis (2 papers, 2018 to 2020). Autosomal recessive disorder caused by pathogenic variants in the CFTR gene (cystic fibrosis transmembrane conductance regulator), which encodes a chloride and bicarbonate channel expressed in epithelial cells, and follow the diagnosis criteria. "In another study, a synonymous mutation in MASP1 in the MASP3 serine protease domain was associated with early Pseudomonas aeruginosa colonization in cystic fibrosis patients." (PMID 29515573, 2018).
dyslipidemia (2 papers, 2014 to 2020). "For example, upregulated expression of Masp1 in obese patients could reflect adipose tissue inflammation, whereas Adam9 overexpression may underlie protective mechanisms against the metabolic syndrome." (PMID 24675842, 2014).
endometriosis (2 papers, 2021 to 2022). The growth of functional endometrial tissue in anatomic sites outside the uterine body. "Changes in cytokine concentrations in peritoneal and follicular fluids were discovered in patients with endometriosis, and a higher level of mannan-binding lectin serine protease 1 (MASP-1) was found both in patients with endometriosis and in patients with SLE6,28,29." (PMID 33436777, 2021). "However, our current understanding of MASP-1 still cannot prove whether a higher amount of MASP-1 is related to the pathogenesis of endometriosis or SLE." (PMID 33436777, 2021).
glaucoma (2 papers, 2019 to 2021). Increased pressure in the eyeball due to obstruction of the outflow of aqueous humor. "In glaucoma human donor eyes, proteomic analysis revealed an upregulation of proteins linked to the lectin pathway, such as MASP1 and MASP2." (PMID 31543759, 2019). "This correlates with up-regulated levels of C1, C8, and C9, as well as MASP1 and MASP2 in retinal tissues from glaucoma donor eyes." (PMID 34943212, 2021).
lung carcinoma (2 papers, 2020 to 2023). "Moreover, an early postoperative reduction in MBL, CL-L1, H-ficolin, M-ficolin, MASP-3, MAp44, MASP-2, and MAp19, but not MASP-1, was recently reported in lung cancer patients undergoing thoracoscopic lobectomy." (PMID 32267878, 2020).
nephritis (2 papers, 2018 to 2025). Inflammation of renal tissue. "However, serum levels of sC5b-9, MBL, and MASP-1 did not significantly differ among IgAV patients with and without nephritis, between the mild and moderate nephritis subgroups, or when any of these groups were compared to HCs." (PMID 40868541, 2025).
Obesity (2 papers, 2014 to 2020). Accumulation of substantial excess body fat. "In this study, the significantly increased expression of MASP1 was observed in patients with simple obesity, hyperglycemia and hyperlipidemia (group b, d and f)." (PMID 32089734, 2020). "To test transcriptional effects of miR-125a down-regulation in human obesity, we quantified the expression of its target genes Tef, Masp1, Rtn2, Ube2l3 and Adam9 in subcutaneous adipose tissue samples of obese patients." (PMID 24675842, 2014). "More specifically Masp1, Tef, Rtn2 and Ube2l3 showed contrasting expression patterns before and after gastric bypass but the effects were statistically significant for Tef only, which highlights a possible specific role of Tef in obesity and IR of obese patients." (PMID 24675842, 2014).
retinal degeneration (2 papers, 2017 to 2025). Degeneration of the retina. "Further studies are needed to define the role of MASP-1 in the development of retinal degeneration in the NaIO3-induced murine dry AMD model." (PMID 40226626, 2025). "Elevated levels of circulating MASP-1 may influence the reduction in choroidal blood flow prior to the development of retinal degeneration in AMD through activation of coagulation factors." (PMID 40226626, 2025). "Our results also indicate that MASP-1 plays a role in the development of NaIO3-induced retinal degeneration in this murine model, although it remains unclear whether its role in the retinal degeneration is through the LP activation." (PMID 40226626, 2025). "The question remains as to why retinal degeneration was attenuated in mice lacking MASP-1 alone, as in mice lacking MASP-3 or MASP-1/3." (PMID 40226626, 2025). "The results presented in this report indicate that the absence of MASP-1 or MASP-3 in a murine dry AMD model has a significantly beneficial effect on the development of the NaIO3-induced retinal degeneration." (PMID 40226626, 2025). "On the other hand, no clear evidence was observed that MASP-1 is involved in retinal degeneration in the NaIO3-induced model via complement activation." (PMID 40226626, 2025). "However, a participation of the lectin pathway in retinal degeneration was proposed as it was shown that MBL and MASP-1 were systemically upregulated in late AMD-patients." (PMID 28676742, 2017). "In the present study, the absence of MASP-1 may have reduced fibrin deposition in the choriocapillaris, which plays an essential role in RPE cell survival, thereby preserving blood flow and alleviating retinal degeneration after NaIO3 injection." (PMID 40226626, 2025).
rheumatoid arthritis (2 papers, 2018 to 2023). A chronic, systemic autoimmune disorder characterized by inflammation in the synovial membranes and articular surfaces. "However, MASP-1 has been shown to play a crucial role in autoimmune diseases such as rheumatoid arthritis and type 1 diabetes." (PMID 37457741, 2023).
staphylococcus aureus infection (2 papers, 2020 to 2022). An infectious process in which the bacteria Staphylococcus aureus is present. "In the early stage of infection, MASP1, MBL2, CFB, loc396877, loc100627396 linked complement and coagulation cascades with Staphylococcus aureus infection pathway, and C7, loc100736136 linked the Staphylococcus aureus infection with the prion disease pathway." (PMID 32632500, 2020).
thrombosis (2 papers, 2022). "Our flow cytometry results confirmed that MASP-1 can induce platelet activation, which is consistent with observations in a murine thrombosis model." (PMID 36032172, 2022).
tuberculosis (2 papers, 2017 to 2018). A chronic, recurrent infection caused by the bacterium Mycobacterium tuberculosis. "Our results, which suggest an important role of MASP1 variants in tuberculosis, were reinforced by the observation of elevated MASP1 serum levels in PTB patients." (PMID 29515573, 2018). "Distribution of allele and genotype frequencies for SNP rs3774275 (MASP1) between controls and tuberculosis patients." (PMID 29515573, 2018). "Further analysis revealed increased MASP1 levels in serum of tuberculosis patients, constituting the first reported association between tuberculosis and this MBL-associated serine protease." (PMID 29515573, 2018). "We next examined radiographic abnormalities in chest X-rays from the TB patients to determine the severity of the disease and to analyze whether the concentrations of MASP1, MASP3, or MAp44 might correlate with the progression of tuberculosis." (PMID 29515573, 2018).
type 1 diabetes (2 papers, 2015 to 2023). "We have recently shown that MASP-1 plasma levels are elevated in patients with type 1 diabetes." (PMID 26645987, 2015). "MASP-1 triggers activation of the lectin pathway and is altered in several autoimmune diseases, such as type 1 diabetes, but its role in HT has not yet been studied." (PMID 37457741, 2023).
acute-on-chronic liver failure (1 paper, 2020). Acute-on-chronic liver failure (ACLF) is an extreme condition during the natural history of chronic HBV infection, with a relatively high short-term mortality. "Interestingly, in HBV-chronically infected patients that undergo acute-on-chronic liver failure, MASP-1 production was found repressed, whereas MASP-2 was up-regulated—being both mostly produced in the liver." (PMID 33643280, 2020).
atherosclerosis (1 paper, 2024). A disease characterized by the build-up of fatty material and calcium deposition in the arterial wall resulting in partial or complete occlusion of the arterial lumen. "Our findings suggest that MASP-1 is a potential drug target in the acute phase of atherosclerosis-related diseases." (PMID 38937560, 2024).
benign thyroid tumors (1 paper, 2023). "Meanwhile, compared with patients with benign thyroid tumors and nodular goiters, an increase in LTF and MASP-1 was also observed in patients with PTC." (PMID 37457741, 2023).
chronic kidney disease (1 paper, 2021). Impairment of the renal function secondary to chronic kidney damage persisting for three or more months. "Therefore, MASP-1/-2 and MAp44 seem to play crucial roles in chronic kidney disease, as well as its associated symptoms and conditions, such as IR and kidney transplantation." (PMID 33729332, 2021).
Cirrhosis (1 paper, 2017). A chronic disorder of the liver in which liver tissue becomes scarred and is partially replaced by regenerative nodules and fibrotic tissue resulting in loss of liver function. "It is relevant to mention that some studies found an association between the progression of active chronic liver disease or cirrhosis with the MBL∗B allele and the MBL/MASP-1 complex in patients with HCV and HBV." (PMID 28408790, 2017).
cleft lip (1 paper, 2025). Congenital defect in the upper lip where the maxillary prominence fails to merge with the merged medial nasal prominences. "We report two novel mutations associated with nonsyndromic cleft lip in adjacent genes EHHADH and MASP1." (PMID 41378467, 2025). "Based on these findings, we propose a novel compound inheritance model for nonsyndromic cleft lip involving the interaction between metabolic processes regulated by EHHADH and immune signaling pathways controlled by MASP1." (PMID 41378467, 2025).
Disseminated intravascular coagulation (1 paper, 2020). Disseminated intravascular coagulation is characterized by the widespread activation of coagulation, which results in the intravascular formation of fibrin and ultimately thrombotic occlusion of small and midsize vessels. "Overall, our findings are in line with studies on septic patients showing low C4 and C3 in non-survivors, and low MASP-1 in patients with disseminated intravascular coagulation (DIC) due to septic shock." (PMID 32082310, 2020).
glomerular disease (1 paper, 2018). "The major role of MASP-1/3 for glomerular disease in this model is supposed to be in the activation of the AP that is initially activated via the CP." (PMID 29892304, 2018). "In addition, glomerular MBL deposition observed in MRL/lpr mice suggests that the activation of the LP, in which MASP-1 plays a significant role, was also involved in their glomerular disease." (PMID 29892304, 2018). "The Masp1/3−/− MRL/lpr mice, however, had significantly less pathological features of glomerular disease compared to their wild-type littermates, with a reduction in mesangial expansion, glomerular inflammation, focal hypercellularity, and crescent formation (reflected in the renal score, p < 0.05)." (PMID 29892304, 2018). "Despite having significantly less albuminuria and pathological features of glomerular disease in the Masp1/3−/− MRL/lpr mice, the absence of MASP-1/3 had no significant beneficial effect on survival in the MRL/lpr mice until the time of sacrifice (week 24)." (PMID 29892304, 2018). "In the present study, the Masp1/3−/− MRL/lpr mice, lacking the LP and AP, had significantly reduced glomerular C3 deposition, pathological glomerular disease and albuminuria compared to their wild-type littermates." (PMID 29892304, 2018).
hereditary angioedema (1 paper, 2017). Hereditary angioedema (HAE) is a genetic disease characterized by the occurrence of transitory and recurrent subcutaneous and/or submucosal edemas resulting in swelling and/or abdominal pain. "The possible pro-inflammatory effects of MASP-1 may contribute to the pathogenesis of inflammatory diseases, where endothelium is also involved, such as atherosclerosis, hereditary angioedema and sepsis." (PMID 28874747, 2017).
hyperopia (1 paper, 2017). A refractive error in which rays of light entering the eye parallel to the optic axis are brought to a focus behind the retina, as a result of the eyeball being too short from front to back. "In addition, MASP1 (from the lectin pathway) was differentially-expressed in a growth-specific manner (down-regulated in late myopia and up-regulated in late hyperopia)." (PMID 28852117, 2017).
immunodeficiencies (1 paper, 2023). "The MBL collagen regions form complexes with the serine proteases MASP-1 and MASP-2 in order to activate complement, and mutations lead to common immunodeficiencies." (PMID 36528062, 2023).
Insulin resistance (1 paper, 2025). Increased resistance towards insulin, that is, diminished effectiveness of insulin in reducing blood glucose levels. "In the biological pathway of insulin resistance, the elevated levels of MASP1, THBS1, GPLD1, AAT, HP, RBP4, ZAG, and ApoA-I may be positively correlated with each other, synergistically exacerbating insulin resistance." (PMID 40162315, 2025).
ischemic stroke (1 paper, 2020). A stroke disorder caused by obstruction of blood flow to the brain, due to thrombotic (local blood clot formation) or embolic (due to a blood clot or other material traveling from another site) event. "In an experimental model of ischemic stroke, we reported that combined deficiency of MASP-1 and MASP-3 did not affect the ischemic outcome, while that of MASP-2 was protective." (PMID 33115535, 2020).
mastitis (1 paper, 2022). Inflammation of breast tissue during lactation or postpartum due to an obstructed duct or infection. "Here, C1, MBL, MASP1, and MASP2 were downregulated in mastitis." (PMID 36335251, 2022).
oral cancer (1 paper, 2023). "MBL associated serine protease 1 (MASP1) has also been proposed as a prognostic factor in HNSCC and oral cancer." (PMID 37705968, 2023).
osteosarcoma (1 paper, 2024). A usually aggressive malignant bone-forming mesenchymal neoplasm, predominantly affecting adolescents and young adults. "MASP1, involved in the immune response, lacks an association with osteosarcoma in the literature but might influence the tumor microenvironment." (PMID 39701601, 2024).